PTP4A1 (protein tyrosine phosphatase 4A1)
Diseases named in the same sentence as PTP4A1 in open-access papers (continued):
Sharing a sentence is not in itself a finding about the gene and the disease.
diabetes (1 paper, 2024). "Loci for the other genes—PTP4A1, APOBR, BMS1P4-AGAP5, MAPK8IP1P1, GYS2, FAM25C, and GK5–were formerly associated with traits involved with comorbidities of OSA, i.e., BMI, weight, triglycerides, blood pressure, stroke, brain volume, cortical thickness, mood, insulin, and diabetes." (PMID 39457448, 2024).
esophageal squamous cell carcinoma (1 paper, 2025). Esophageal squamous cell carcinoma (ESCC) is a type of esophageal carcinoma (EC) that can affect any part of the esophagus, but is usually located in the upper or middle third. "WTAP positively regulates the expression of m6A target PTP4A1, activates the AKT mTOR pathway, and promotes esophageal squamous cell carcinoma (ESCC) cell proliferation." (PMID 41256854, 2025).
fibrosis (1 paper, 2017). the formation of excess fibrous connective tissue in an organ or tissue in a reparative or reactive process. "In this study, we assess the expression of all PTPs14 in DFs of patients with dcSSc, in whom the occurrence of fibrosis is generally early and rapidly progressive, finding that PTP4A1 is overexpressed in dermal SSc fibroblasts." (PMID 29057934, 2017). "PTP4A1 and its close homolog PTP4A2 are critical promoters of TGFβ signaling in primary dermal fibroblasts and of bleomycin-induced fibrosis in vivo." (PMID 29057934, 2017).
Hepatic steatosis (1 paper, 2023). Steatosis is a term used to denote lipid accumulation within hepatocytes. "Deficiency of PTP4A1 in mice accelerates hepatic steatosis in mice fed a high-fat (HF) diet and leads to the disruption of glucose homeostasis with the reduction of GLUT2 on the plasma membrane of hepatocytes." (PMID 36793871, 2023). "To investigate how PTP4A1 deficiency in mice induces hepatic steatosis, we analyzed the levels of transcripts involved in lipid metabolisms." (PMID 36793871, 2023). "Here, we identified PTP4A1 as a negative regulator in the pathogenesis of hepatic steatosis through activation of the CREBH/FGF21 axis." (PMID 36793871, 2023).
Hyperglycemia (1 paper, 2023). An increased concentration of glucose in the blood. "Lacking PTP4A1 in mice fed an HF diet exhibited hepatosteatosis and hyperglycemia, which were recovered by liver-specific PTP4A1 or systemic FGF21 overexpression." (PMID 36793871, 2023). "In the current study, we identified that Ptp4a1-/- mice fed an HF diet revealed hyperglycemia and fatty liver compared to controls." (PMID 36793871, 2023). "Instead of insulin resistance, we guessed that PTP4A1 deficiency in mice induced fat accumulation in the liver by feeding an HF diet or fasting, followed by decreased GLUT2 translocation on the hepatocyte surface, leading to hyperglycemia." (PMID 36793871, 2023). "In addition, liver-specific PTP4A1 expression ameliorated HF diet-induced hepatosteatosis and hyperglycemia in wild-type (WT) mice." (PMID 36793871, 2023). "Next, we tested whether FGF21 overexpression in Ptp4a1-/- mice could ameliorate an HF diet-induced hyperglycemia and NAFLD." (PMID 36793871, 2023). "Finally, liver-specific PTP4A1 expression ameliorated an HF diet-induced hepatosteatosis and hyperglycemia in wild-type mice." (PMID 36793871, 2023). "Finally, we proved that liver-specific PTP4A1 expression ameliorated HF diet-induced hepatosteatosis and hyperglycemia in WT mice." (PMID 36793871, 2023). "In summary, our results establish hepatic PTP4A1-mediated activation of the CREBH/FGF21 axis as a novel therapeutic strategy in NAFLD and hyperglycemia." (PMID 36793871, 2023). "Liver-specific PTP4A1 expression, followed by augmentation of FGF21 levels, reduced HF diet-induced hepatosteatosis and hyperglycemia in WT mice." (PMID 36793871, 2023).
Insulin resistance (1 paper, 2023). Increased resistance towards insulin, that is, diminished effectiveness of insulin in reducing blood glucose levels. "In fasting conditions, homeostatic model assessment-insulin resistance (HOMA-IR) was significantly increased in Ptp4a1-/- mice compared to WT mice after an HF diet." (PMID 36793871, 2023). "Therefore, we could not conclude that PTP4A1 depletion in mice fed an HF diet develops insulin resistance." (PMID 36793871, 2023).
lymph node metastasis (1 paper, 2023). "The results of this study showed that both CTC subtypes and PTP4A1 expression levels were associated with the TNM stage and lymph node metastasis of tumors." (PMID 38134119, 2023). "The receiver operating characteristic curve showed that TNM stage and lymph node metastasis had a high predictive efficiency for PTP4A1+MCTCs, with an area under the ROC curve of 0.725." (PMID 38134119, 2023). "Therefore, we constructed a prediction model to explore the predictive efficacy of TNM staging and lymph node metastasis for PTP4A1+MCTCs and plotted ROC curves." (PMID 38134119, 2023). "The results showed that PTP4A1+MCTCs were significantly correlated with clinical TNM staging and lymph node metastasis (P = .036 and P = .013, respectively)." (PMID 38134119, 2023).
melanoma (1 paper, 2021). A malignant, usually aggressive tumor composed of atypical, neoplastic melanocytes. "The antagonistic pathogenesis of vitiligo in relation to cancer specific enhanced cell motility and/or metastasis on typical melanoma predilection sites underlines a plausible involvement of RCBTB1, LITAFD, NUBPL, and PTP4A1." (PMID 34696794, 2021).
osteoporosis (1 paper, 2024). A condition of reduced bone mass, with decreased cortical thickness and a decrease in the number and size of the trabeculae of cancellous bone (but normal chemical composition), resulting in increased fracture incidence. "After the non-SDEGs added by GeneMANIA to establish the PPI network removed, six up-regulated SDEGs (HIST1H3G, HIST1H2BO, PTP4A1, FAM46A, MT1G and TNFSF9) and one down-regulated SDEG (PMAIP1) were identified as potential hub genes in the pathogenesis of osteoporosis." (PMID 38372699, 2024).
Peritoneal Fibrosis (1 paper, 2023). Disorder characterized by a wide range of structural changes in PERITONEUM, resulting from fibrogenic or inflammatory processes. "PTP4A1 was the most statistically significant biomarker associated with PD vintage and loss of peritoneal membrane function, caused by peritoneal fibrosis, due to the unphysiological composition of PD fluids." (PMID 37762196, 2023). "As peritoneal fibrosis is a frequent evolution of PD, which can limit the efficacy of dialytic treatment, it would be useful to validate PTP4A1 as a prognostic biomarker to predict the progression of renal fibrosis in PD." (PMID 37762196, 2023).
scleroderma (1 paper, 2022). Scleroderma is a rare autoimmune connective tissue disorder characterized by abnormal hardening of the skin and, sometimes, other organs. "Here, we assessed whether oxidation of PTP4A1 modulates its profibrotic action and found that PTP4A1 forms a complex with the kinase SRC in scleroderma fibroblasts, but surprisingly, oxidative stress enhanced rather than reduced PTP4A1’s association with SRC and its profibrotic action." (PMID 35451370, 2022).
type 2 diabetes (1 paper, 2023). "To evaluate whether PTP4A1 affects the regulation of obese-mediated metabolic diseases such as type 2 diabetes and NAFLD, we generated Ptp4a1-/- mice by CRISPR/Cas9 system and placed Ptp4a1-/- mice and WT littermates on an HF diet for 12 weeks." (PMID 36793871, 2023).
vitiligo (1 paper, 2021). Generalized well circumscribed patches of leukoderma that are generally distributed over symmetric body locations and is due to autoimmune destruction of melanocytes. "In total, we propose the genes NUBPL, PHF11, SETDB2, RCBTB1, PTP4A1, and at a weaker replication level the genes LITAFD, CARHSP1 and OR2C1 as possible candidates for vitiligo-like depigmentation in grey horses." (PMID 34696794, 2021).
cancer (24 papers, 2014 to 2025). A tumor composed of atypical neoplastic, often pleomorphic cells that invade other tissues. "The 6q12 locus harbors PTP4A1, a protein tyrosine phosphatase, previously implicated in cancer." (PMID 35706047, 2022). "PTP4A1 is highly expressed in several cancer types, and the overexpression of PTP4A1, which is associated with aggressive tumor characteristics, may be regulated by the PI3K/AKT pathway." (PMID 34226298, 2021). "Therefore, the identification of underlying mechanism of invasion-promoting effect of PTP4A1 in ICC needs a cancer-specific exploration." (PMID 27655691, 2016). "PTP4A3 is the most frequently overexpressed PTP4A phosphatase in different cancer types, although some cancers also co‐express PTP4A1 and/or PTP4A2." (PMID 40657934, 2025). "Mechanistically, GINS2 regulates cancer-cell proliferation via the phosphatase PTP4A1 (PRL-1), establishing a direct GINS2→PTP4A1 link." (PMID 41322418, 2025). "STK11 is a tumor suppressor involved in cell motility and metabolism and NFE2L2 plays a key role in oxidative stress response, while PTP4A1 has been recently identified as a novel therapeutic target in cancer." (PMID 38191367, 2024). "Together, these findings reveal new roles for PTP4A1 during mitochondrial metabolic reprogramming in cancer." (PMID 37773151, 2023). "Protein tyrosine phosphatase 4A1 (PTP4A1) is a membrane-associated protein tyrosine phosphatase that is subject to prenylation and upregulated in an array of cancers." (PMID 37773151, 2023). "The level of PTP4A1 expression affects the degree of malignancy of tumors and the malignant biological behavior of cancer cells." (PMID 35872698, 2022). "The function of BNIP3 is similar to that of PTP4A1, which includes the inhibition of cancer aggression." (PMID 34226298, 2021). "PTP4A1 can enhance cell proliferation, cell motility, and invasive activity and promote cancer metastasis." (PMID 33718231, 2021). "Amongst the genes directly regulated by STAiR18 and STAT3 we identified several targets involved in cell cycle progression and cancer cell survival, like the protein tyrosine phosphatase type 4 member 1 (PTP4A1) and the transmembrane protein 45A (TMEM45A)." (PMID 32041604, 2020). "Previous studies have reported that PTP4A1 can promote cancer migration and invasion via the ERK1/2 signaling pathway." (PMID 32457332, 2020). "PTP4A1 and PTP4A3 have been reported to promote activation of Rho and of its major effector Rho-associated protein kinase (ROCK) in cancer cells." (PMID 29057934, 2017). "The protein tyrosine phosphatase PTP4A1 is a key molecule that activates tyrosine phosphorylation, which is important for cancer progression and metastasis." (PMID 27655691, 2016). "The mechanisms for invasion-promoting effect of PTP4A1 in different types of cancers are highly different." (PMID 27655691, 2016). "Our analysis indicated that tyrosine phosphatase PTP4A1 (also called PRL1, phosphatase of regenerating liver 1) may have an oncogenic role in STK11-inactivated NSCLC and that PTP4A1-dependent effects of FTIs in these cancers should be further evaluated." (PMID 39995872, 2025). "Given the central role of interferon signaling in the interplay between the immune system and cancer cells, it is tempting to speculate that overexpression of PTP4A1 could affect anti-cancer immune responses." (PMID 39995872, 2025). "Whether the mechanism(s) by which PTP4A1 promotes cancer cell growth differ according to cancer type remain undefined." (PMID 37773151, 2023). "PTP4A1 expression in cancer samples was higher than in healthy controls (P < 0.05)." (PMID 35872698, 2022). "MT2A and TRIM31 which were engaged in IFN-γ signaling, CDC6, SGK1 and PTP4A1 genes, presented a homogeneous expression pattern in both test and Validation datasets, although our results were contradictory to other studies in different cancers." (PMID 34249670, 2021).
cancer (continued). "Moreover, down-regulation of endogenous PTP4A1 expression in cancer cells results in reduced proliferation and suppressed cell motility." (PMID 27655691, 2016). "Future targeted studies are needed to reveal the exact mechanism of PTP4A1 effects on IFN signaling, the potential connection to cell fitness, and the clinical value of these findings in relation to cancer and inflammation." (PMID 39995872, 2025). "While this observation was unexpected based on the reports that both PTP4A1 and PTP4A2 promote ERK signaling in cancer cells, it does support the possibility that, in NHDF lines, only PTP4A1 controls TGFβ signaling through the ERK pathway." (PMID 29057934, 2017). "Therewith, we reveal the functional role of a farnesylation substrate PTP4A1, a new synergistic drug combination of an FTI and a ferroptosis-inducing drug, and new cancer subgroups that may benefit from FTI treatment." (PMID 39995872, 2025). "OSCC cells were co-transfected with sh-PTP4A1 and PKM2 to investigate whether PKM2 could restore the metastatic phenotypes of OSCC cancer cells silenced for PTP4A1 expression." (PMID 37773151, 2023). "Based on these results together with their known inhibitory effects on cancer cell proliferation and metastasis, combined treatment with both PLK1 and PTP4A1 inhibitors could be an effective therapy for metastatic breast cancer." (PMID 31097707, 2019). "As EMT is strongly hypothesized as a driver of cancer cell motility and ICC shares similar oncogenic processes with HCC, we explore and indeed found that E-cadherin was also regulated by PTP4A1 in ICC cells." (PMID 27655691, 2016). "PTP4A1 has reported pro-metastatic activity in OSCC cells through its ability to regulate filamentous action dynamics, enhanced matrix metalloproteinase expression, and PI3K/AKT signaling in cancer cells, thereby promoting epithelial-mesenchymal transition (EMT) processes." (PMID 37773151, 2023). "We further showed that PTP4A1 interacts and co-localizes with PKM2, a pivotal glycolytic enzyme that also executes non-metabolic signaling functions in cancer." (PMID 41322418, 2025).
tumor (21 papers, 2013 to 2025). "In addition, tumors from Aire−/− mice had lower levels of expression of Ptp4a1 and Meis2 which have been shown to promote tumor progression and are associated with poor survival." (PMID 32641748, 2020). "Using TCGA PanCancer Atlas data accessed via cBioPortal, we assessed mRNA expression (z-score ≥2) in tumor samples relative to normal tissue for all PRLs (PTP4A1–3) and CNNMs (CNNM1–4)." (PMID 40463094, 2025). "We demonstrate that GINS2 promotes tumor cell proliferation, migration, and invasion, potentially involving interaction with PTP4A1 and PKM2." (PMID 41322418, 2025). "PTP4A1 belongs to a family of liver cell regeneration phosphatase factor proteins and plays an important role in tumor development." (PMID 42135822, 2025). "In OSCC, the overexpression of PTP4A1 increased cell growth and invasion in vitro, and enhanced tumor progression in vivo." (PMID 37773151, 2023). "PTP4A1 silencing was found to strongly suppress tumor progression, volume and weight compared to sh-NC cells (P < 0.01, and P < 0.001)." (PMID 37773151, 2023). "To confirm that the inhibition of PTP4A1 prevents OSCC tumor growth and metastasis, we implanted OSCC-25 cells expressing sh-PTP4A1 into mice and compared tumor growth." (PMID 37773151, 2023). "PTP4A1+mixed tumor cells had strong predictive value for the efficacy of neoadjuvant therapy, with a sensitivity of 94.7% and a specificity of 63.6%." (PMID 38134119, 2023). "PTP4A1 is a family member of liver cell regeneration phosphatase factor proteins, which plays an essential role in tumor development." (PMID 35872698, 2022). "Protein tyrosine phosphatase type IVA 1 belongs to a group of three prenylated PTPs (PTP4A1/2/3), which support growth and migration of tumor cells." (PMID 34696794, 2021). "The highlighted genes PHF11, SETDB2, CARHSP1 and LITAFD, are associated with the innate immune system, while the genes RCBTB1, LITAFD, NUBPL, PTP4A1, play a role in tumor suppression and metastasis." (PMID 34696794, 2021). "PTP4A1 (also known as phosphatase of regenerating liver 1), which is reportedly upregulated in many tumor cell lines, including HeLa cells, promotes cell migration and invasion." (PMID 32457332, 2020). "IHC (3 samples per group) confirmed that PTP4A1 was elevated in the tumor tissues of the OV-cNRIP1 group, compared with those of the control group." (PMID 32457332, 2020). "High PTP4A1 expression significantly correlated with aggressive tumor characteristics, including larger tumor size (P = 0.020), lymph node metastasis (P = 0.002) and advanced tumor stage (P = 0.004)." (PMID 27655691, 2016). "Additionally, we found that miR-629-3p induced tumor suppression by regulating PTP4A1 and the ERK1/2 pathway." (PMID 32457332, 2020). "Here, we showed that PTP4A1 was frequently overexpressed in ICC versus adjacent non-tumor tissues." (PMID 27655691, 2016). "PTP4A1 was scored as strong or moderate intensity in 64.3% (207 of 322: strong, n=47; moderate, n=160) of tumor tissues, whereas only 23.0% (74 of 322: strong, n=35; moderate, n=39) of corresponding adjacent normal intrahepatic biliary tissues was scored as strong or moderate intensity." (PMID 27655691, 2016). "Thus, we hypothesized that miR-629-3p acts as a tumor suppressor in CC by targeting PTP4A1 and regulating the ERK1/2 pathway." (PMID 32457332, 2020). "We show that PTP4A1 is frequently overexpressed in OSCC cells and tissues compared to adjacent non-tumor tissue." (PMID 37773151, 2023). "Immunohistochemically, PTP4A1 staining intensity was weak in adjacent normal intrahepatic biliary tissues, as compared with marked up-regulation in ICC tumor tissues." (PMID 27655691, 2016). "PTP4A1 is higher expressed in non-polyp mucosa from CRSwNP patients compared to healthy controls, as well as in tumours and is strongly down-regulated upon tetrodotoxin treatment." (PMID 37085563, 2023).
tumor (continued). "In addition to CORO1A, THBS1, PTP4A1, IL6, and CXCL16, the other nine genes were also upregulated in tumor tissues in TCGA." (PMID 32883954, 2020). "Previous studies have showed that up-regulation of the PRLs, especially PTP4A1 and PTP4A3 could promote cell invasion, migration and metastasis during tumor development and progression." (PMID 29100406, 2017). "PTP4A1, PTP4A2, and PTP4P3 are three closely related small PTPs which drawn attention to us about their functions in tumor cell proliferation, including promotion of tumor migration, invasion, and metastasis." (PMID 29100406, 2017). "Moreover, through forced overexpression and knock-down of PTPT4A1, we demonstrated that PTP4A1 could significantly promote ICC cells proliferation, colony formation, migration, and invasion in vitro, and markedly enhance tumor progression in vivo." (PMID 27655691, 2016). "Moreover, KRAS‐driven tumours may compensate for the lack of PTP4A1–3 activity by increasing RAS and PI3K signalling, coupled with autophagy addiction." (PMID 40657934, 2025). "Interestingly, there was a lower expression of PTP4A1 in AciCC and DC, and all these tumors that expressed PTP4A1 were the non-myoepithelial types of SGTs, which suggested that PTP4A1 might function in tumor epitheliums, but not myoepithelial cells." (PMID 36527158, 2022). "PTP4A1 belongs to a sub-class of three prenylated PTP (PTP4A1/2/3), which promote growth and migration of tumor cells through mechanisms that are not understood but probably include regulation of growth factor signaling." (PMID 29057934, 2017). "The lack of functional antibodies for PTP4A1 and PTP4A2 precluded evaluating the tumor protein levels for these family members." (PMID 23555575, 2013).
hematological cancers (1 paper, 2016). "The phosphatases of regenerating liver 1, 2, and 3 (PRL1–3, also known as PTP4A1–3) are members of the PTP family that are highly expressed in the majority of human solid tumors as well as in hematological cancers (2, –, 4)." (PMID 26969161, 2016).